RARG (retinoic acid receptor gamma)
Diseases named in the same sentence as RARG in open-access papers (continued):
Sharing a sentence is not in itself a finding about the gene and the disease.
pancreatic ductal adenocarcinoma (4 papers, 2020 to 2023). An infiltrating adenocarcinoma that arises from the epithelial cells of the pancreas. "Overexpression of RARγ in pancreatic ductal adenocarcinoma tissue and high-grade precancerous lesions was linked to a poor patient prognosis and blocking RARγ signalling supressed the proliferation of cancer cells." (PMID 37082619, 2023). "Treatment of five lumen-forming patient-derived pancreatic ductal adenocarcinoma organoids with siRNA revealed that RARγ signalling underlies their proliferation by promoting cell cycle progression." (PMID 36768694, 2023). "The levels of RARγ transcripts were significantly higher in pancreatic ductal adenocarcinoma tissue and high-grade precancerous lesions than in normal pancreatic tissue." (PMID 36768694, 2023). "Blocking of RARγ signalling via siRNA suppressed the cell proliferation of the pancreatic ductal adenocarcinoma cell lines PK-1 and Panc-1, arresting cells in G1 of the cell cycle without causing apoptosis." (PMID 36768694, 2023). "RARγ was required for the proliferation of pancreatic ductal adenocarcinoma cells as CRISP-9-Cas9 knockout in PANC1 cells led to cycle arrest at S phase and apoptosis, and tumor formation by RARG-deficient cells in NOD/SCID mice was suppressed." (PMID 37569466, 2023).
renal carcinoma (4 papers, 2014 to 2026). A carcinoma arising from the epithelium of the renal parenchyma or the renal pelvis. "MiR-30a expression was widely downregulated in patients’ colorectal, gastric, hepatocellular, lung, oral, pancreatic, prostate, and renal cancer tissues, and accordingly colorectal, hepatocellular, pancreatic, and renal cancer cells are known to overexpress RARγ." (PMID 37569466, 2023). "The microRNA (miR) 30a-5p downregulates expression of RARγ, and miR-30a/miR-30a-5p is a tumor suppressor for breast, colorectal, gastric, hepatocellular, lung, oropharyngeal, ovarian, pancreatic, prostate, and renal cancer." (PMID 37569466, 2023).
esophageal cancer (3 papers, 2020 to 2023). A primary or metastatic malignant neoplasm involving the esophagus. "However, no report has clarified the relationship between the prognosis and expression or mutation of RARγ in esophageal cancer." (PMID 32556644, 2020). "Future studies focusing on RARγ signaling as well as these other relevant signals may provide some insight into not only esophageal differentiation but also the pathogenesis of esophageal cancer." (PMID 32556644, 2020).
gastric cancer (3 papers, 2003 to 2024). A primary or metastatic malignant neoplasm involving the stomach. "In gastric cancer, high expression levels of RARα/RARβ/RARγ/RXRβ transcripts are associated with poor clinical and molecular characteristics as well as with reduced overall-survival." (PMID 39323992, 2024). "Finally, we established associations of the RARα, RARβ, RARγ and RXRβ levels with a detrimental effect on the overall-survival of gastric cancer patients." (PMID 39323992, 2024). "By converse, our data indicated that gastric cancer samples tended to express low levels of the RARγ and RXRγ mRNAs." (PMID 39323992, 2024). "In this single-institution/retrospective clinical and translational study (RAR-GASTRIC), we define the expression of RARα, RARβ, RARγ, RXRα, RXRβ and RXRγ in stomach tumors with the use of archival tissue samples obtained from gastric cancer patients." (PMID 39323992, 2024). "The work supports the idea that RARα, RARβ, RARγ and RXRβ represent potential prognostic markers and actionable therapeutic targets in the context of the personalized treatment of gastric cancer." (PMID 39323992, 2024). "In this study, we determine the RNA expression of the six isoforms of Retinoic-Acid-Receptors (RARα/RARβ/RARγ/RXRα/RXRβ/RXRγ) in view of their potential use as gastric cancer progression markers and/or therapeutic targets." (PMID 39323992, 2024). "Taken together, our data support the idea that the tumor levels of RARα, RARβ, RARγ and RXRβ mRNAs are potential determinants of a low overall-survival rate in gastric cancer." (PMID 39323992, 2024). "Our data are consistent with the idea that RARα, RARβ, RARγ and RXRβ represent potential prognostic markers and therapeutic targets of gastric cancer." (PMID 39323992, 2024). "To identify the RAR isoform(s) underlying the anti-proliferative action of the retinoid, initially, we evaluated the constitutive expression of RARα, RARβ, RARγ, RXRα, RXRβ and RXRγ mRNAs in our gastric-cancer cell-lines." (PMID 37951921, 2023). "In a previous report on RARs' and RXRs' Northern mRNA expression level of gastric cancer cell lines, enhanced expression of RARα/RARγ was observed in SC-M1 cells and enhanced RARβ level was found in TSGH cells." (PMID 12671705, 2003). "Finally, we observe a worse overall-survival in gastric cancer patients characterized by high RARα/RARβ/RARγ/RXRβ mRNA levels." (PMID 39323992, 2024).
head and neck cancer (3 papers, 2025). A primary or metastatic malignant neoplasm affecting the head and neck. "Ligand activated RARγ accelerated the cell cycle progression of head and neck cancer cell line cells, and this required CDK7-dependent phosphorylation of RARγ." (PMID 40362593, 2025). "Head and neck cancer patients may benefit because active RARγ isoforms promote head and neck cancer proliferation." (PMID 40362593, 2025). "This is also supported by our finding that FOSL1 (FRA1), a subunit of the transcription factor AP-1 and a known driver of metastasis in head and neck cancer, is upregulated in RARGKO cells and contains RARγ peaks within its regulatory regions in PAR cells." (PMID 41274504, 2025). "It was clearly shown that the RARγ1, 2, 4 were the predominant RARγ isoforms expressed in immortalized SG, DOK, and head and neck cancer cells." (PMID 39744424, 2025).
metastatic disease (3 papers, 2021 to 2025). "Findings from immunohistology studies have led to a link between high RARγ expression and aggressive and metastatic disease." (PMID 40362593, 2025). "In vitro studies suggest that RARγ-selective and pan-RAR antagonists provoke the death of CSCs by necroptosis and point to antagonism of RARγ as a potential strategy to treat metastatic disease and relapse, and perhaps provide a cure for some cancers." (PMID 33807298, 2021).
myeloproliferative disorder (3 papers, 2019 to 2023). A clonal hematopoietic stem cell disorder, characterized by proliferation in the bone marrow of one or more of the myeloid (i.e., granulocytic, erythroid, megakaryocytic, and mast cell) lineages. "Myeloproliferative disorders have been reported after loss of expression of the retinoic acid receptor-gamma (RARγ) by BM-MSCs in an altered murine microenvironment." (PMID 34830855, 2021). "Moreover, the deletion of the Retinoic Acid Receptor γ (RARγ) in mice resulted in a chronic myeloproliferative disorder." (PMID 31861268, 2019). "However, transplantation of normal hematopoietic cells into the RARγ-microenvironment resulted in a myeloproliferative disorder in the transplanted cells, revealing the capability of the microenvironment to be the only cause of hematopoietic disorders." (PMID 31861268, 2019).
acute leukemia (2 papers, 2014 to 2020). A clonal (malignant) hematopoietic disorder with an acute onset, affecting the bone marrow and the peripheral blood. "Similar to other RARG fusion gene with AML, this kind of acute leukemia showed the clinical feature with coagulopathy, and the morphology, immunophenotyping were mimicking with APL." (PMID 33019444, 2020).
cardiomyopathy (2 papers, 2022 to 2025). A disease of the heart muscle or myocardium proper. "Despite that replication studies of the association of the RARG variant with cardiotoxicity were inconsistent, a functional study in iPSC-derived cardiomyocytes showed that the variant RARG increases sensitivity to doxorubicin-induced cardiomyopathy." (PMID 36536332, 2022). "Most research was done on doxorubicin-induced cardiomyopathy and for seven genetic variants in CELF4, GPR35, HAS3, RARG, SLC22A17, SLC22A7 and SLC28A3, replication studies were performed without consistent results." (PMID 36536332, 2022). "As a result, 20 studies were included (15 case-control and five cohorts), revealing several genes and variants associated with cardiomyopathy, among which, SLC28A3-rs7853758, RARG-rs2229774, P2RX7-rs208294 and P2RX7-rs3751143 variants gave the most consistent findings." (PMID 40413218, 2025).
clear cell renal cell carcinoma (2 papers, 2023). "RARγ and RARβ were upregulated in clear renal cell carcinoma, as seen from a bioinformatics analysis and the use of quantitative PCR." (PMID 37082619, 2023). "Around half of the patients with clear cell renal cell carcinoma were observed to over-express RARγ, as seen from qPCR and a bioinformatics analysis." (PMID 36768694, 2023).
colorectal tumor (2 papers, 2025). "In colorectal tumors, IL-6 signaling promotes lactylation-mediated repression of retinoic acid receptor gamma (RARγ) in macrophages." (PMID 40843350, 2025). "Recent studies have demonstrated that lactylation drives the downregulation of retinoic acid receptor gamma (RARγ) in TAMs, thereby enhancing IL‐6 levels in the TME and promoting tumor growth and proliferation through the activation of STAT3 signaling in colorectal tumor cells." (PMID 40443721, 2025).
dermatitis (2 papers, 2013 to 2021). An inflammatory process affecting the skin. "Parallel to ATRA skin content, elevated mRNA levels of RARγ and RXRα, both the most abundant retinoid receptors in skin, were evidenced only in allergen-induced dermatitis." (PMID 23977003, 2013).
oral cavity SCC (2 papers, 2021 to 2025). "Since CD1530 has been shown to reduce the development of oral cavity SCC, here, we explored the gene expression pathways regulated by RARγ in a human oral cavity SCC line to elucidate how RARγ achieves these positive therapeutic results." (PMID 41274504, 2025). "Although data indicate that RARγ agonism is antitumorigenic in oral cavity squamous cell carcinoma (OCSCC), the specific, primary gene targets of RARγ remain poorly characterized." (PMID 41274504, 2025).
osteoarthritis (2 papers, 2020 to 2022). A noninflammatory degenerative joint disease occurring chiefly in older persons, characterized by degeneration of the articular cartilage, hypertrophy of bone at the margins and changes in the synovial membrane. "Alteration of the osteoarthritis pathway due to RARγ agonist treatment was associated with the up-regulation of catabolic genes (ADAMTS5, HES1, and MMP13), inhibition of cartilage matrix anabolic genes (COL2A1, ACAN, and SOX9) and the up-regulation of death genes (CASP4)." (PMID 32294904, 2020). "Further studies need to be conducted to link RARγ-agonist treatment to a pro- or anti-osteoarthritis pathway action." (PMID 32294904, 2020). "The RARγ-agonist treatment significantly altered the osteoarthritis pathway, however, the IPA analysis did not give a significant level of positive or negative Z-score to determine up- or down-regulation of this pathway." (PMID 32294904, 2020).
osteosarcoma (2 papers, 2022 to 2023). A usually aggressive malignant bone-forming mesenchymal neoplasm, predominantly affecting adolescents and young adults. "The RARg agonist CD437 strongly induces the arrests of cell growth in all three osteosarcoma cell lines as well as in osteoblasts." (PMID 36681687, 2023). "In addition to RARa, RARb and RARg are also thought to be activated by ATRA in osteosarcoma cells." (PMID 36681687, 2023). "Therefore, in addition to RARa activation, whether ATRA-mediated inhibition of osteosarcoma cell growth may also be partially attributed to RARg activation requires further study." (PMID 36681687, 2023). "The antagonists of RARa and RARg exhibit no inhibitory effect on osteosarcoma cell growth." (PMID 36681687, 2023).
ovarian tumor (2 papers, 2008 to 2022). "RARG was highly expressed in ovarian tumors and was an independent predictor of poor overall survival outcomes." (PMID 36523991, 2022).
psoriasis (2 papers, 2008 to 2024). An autoimmune condition characterized by red, well-delineated plaques with silvery scales that are usually on the extensor surfaces and scalp. "Psoriasis, a skin disease has been successfully treated with Tazarotene, a retinoid with selective activity towards RARβ and RARγ, indicating a specific role for RARγ and/or RARβ in the disease." (PMID 18398471, 2008).
squamous cell carcinoma (2 papers, 2022 to 2025). A carcinoma arising from squamous epithelial cells. "Loss of RARG expression can promote v-Ha-Ras-induced squamous cell carcinoma." (PMID 36523991, 2022). "Our results emphasize the importance of selective RARγ agonism in therapeutic design and additionally provide a foundation for future investigations into nuclear receptor cross talk in squamous cell carcinoma." (PMID 41274504, 2025). "RARγ suppresses transformation/tumorigenesis in mouse keratinocytes, and RA-induced apoptosis and cell-cycle arrest in transformed mouse keratinocytes depend on a functional RARγ; moreover, RARγ expression decreases during human squamous cell carcinoma (SCC) progression." (PMID 41274504, 2025).
cervical tumors (1 paper, 2024). "Again, in the cervical tumors, RARG is highly expressed, while the salivary gland tumor cells exhibit the highest expression of ADRB2 (Adrenoceptor Beta 2), implicating its crucial function in glandular processes." (PMID 39766077, 2024).
cholesteatoma (1 paper, 2023). A pathologic process characterized by the proliferation of keratinizing squamous epithelium resulting in the accumulation of keratin and cells in the middle ear and/or mastoid.
cleft palate (1 paper, 2011). Cleft palate is a fissure type embryopathy that affects the soft and hard palate to varying degrees. "In this study, we used mouse embryos harboring null mutations in the genes coding for RALDH3, RARA, or RARG to unravel the possible interaction between atRA and TCDD during palate development and to reassess the etiology of TCDD-induced cleft palate." (PMID 21807577, 2011). "We also excluded the possibility that TCDD acts through binding to, and activating, RARG because ablation of Aldh1a3 was sufficient to prevent TCDD-induced cleft palate." (PMID 21807577, 2011). "Our results indicate that atRA-activated RARG controls the expression of AHR at GD10.5 in the developing palate, which in turn appears necessary for TCDD to induce cleft palate." (PMID 21807577, 2011). "Together, our findings that a) RARG, but not RARA, is mandatory for TCDD to induce cleft palate and b) RAR directly controls Ahr gene expression imply that the AHR-expressing cells at the origin of the malformation are necessarily distributed within the domain where RARG is operational." (PMID 21807577, 2011).
colorectal adenocarcinoma (1 paper, 2021). The most common type of colorectal carcinoma. "Although a clear understanding of the role of RARγ in necroptosis remains to be established, the function of a cytosolic form of RARγ seems to be important for TNF-induced cell death in HT-29 colorectal adenocarcinoma cells." (PMID 33807298, 2021).
erythroleukemia (1 paper, 2017). Acute erythroid leukemia characterised by the presence of at least 50% erythroid precursors and at least 20% myeloblasts in the bone marrow. "Our study is the first to report that a RARγ agonist augments cellular adhesion, dampens cellular proliferation, and increases β1 integrin cell surface expression in a human erythroleukemia cell line." (PMID 28552962, 2017).
esophageal SCC (1 paper, 2005). "In the present study, protein levels of RARγ were found to be significantly higher in normal esophageal tissue of patients with esophageal SCC in comparison to controls." (PMID 16277658, 2005). "Analysis revealed a significantly higher protein concentration of RARγ in normal unaffected tissue of patients with esophageal SCC in comparison to controls." (PMID 16277658, 2005). "Interestingly, only levels of RARγ were found to be significantly lower by ~68% in esophageal SCC in comparison to normal esophageal tissue (p = 0.046)." (PMID 16277658, 2005).
glioma (1 paper, 2022). A benign or malignant brain and spinal cord tumor that arises from glial cells (astrocytes, oligodendrocytes, ependymal cells). "Literature data showed that glioma cell lines express RARγ, while primary cultures of biopsy material from human GBMs expressed RARγ and RXRα." (PMID 36010607, 2022). "Additionally, ATRA has a pro-proliferative and pro-survival effect on stem-like glioma cells mediated by RARα and RARγ." (PMID 36010607, 2022).
Hyperglycemia (1 paper, 2019). An increased concentration of glucose in the blood. "We have recently shown both in diet-induced and genetic obesity models that agonists for RARβ2, but not RARγ, decreased hepatic steatosis, inflammation, and hyperglycemia." (PMID 30677086, 2019).
liver steatosis (1 paper, 2022). "In contrast to the effects of RARβ2 selective agonists on liver steatosis in HFD-induced NAFLD models, the RARα agonist Am 80 exacerbates and the RARγ agonist CD1530 has no major effect on liver steatosis in these models, respectively." (PMID 35406069, 2022).
lung adenocarcinoma (1 paper, 2021). A carcinoma that arises from the lung and is characterized by the presence of malignant glandular epithelial cells. "Another study of retinoic acid reported that increased RARα and RARγ could mediate growth inhibition by all-trans retinoic acid (ATRA) in H1792 cells, a lung adenocarcinoma cell line." (PMID 33735188, 2021).
myeloma (1 paper, 2022). "RARG activation sensitizes human myeloma cells to carfilzomib treatment through the OAS-RNase L innate immune pathway." (PMID 36523991, 2022).
nephrotic syndrome (1 paper, 2026). A collection of symptoms that include severe edema, proteinuria, and hypoalbuminemia; it is indicative of renal dysfunction. "Differentially altered expression of transcripts of retinoic acid receptors α, β, γ (Rarα, β, γ), which mediate the actions of all-trans retinoic acid (RA), is observed in glomeruli of nephrotic syndrome (NS) patients vs normal individuals, with Rarβ reduced and both RARα and RARγ increased." (PMID 41364431, 2026).
non-small cell lung carcinoma (1 paper, 2015). A group of at least three distinct histological types of lung cancer, including non-small cell squamous cell carcinoma, adenocarcinoma, and large cell carcinoma. "Decreased RARγ has also been found to be depleted in 41 % of non-small-cell lung cancer." (PMID 26462767, 2015).
osteoporosis (1 paper, 2023). A condition of reduced bone mass, with decreased cortical thickness and a decrease in the number and size of the trabeculae of cancellous bone (but normal chemical composition), resulting in increased fracture incidence. "And we provided 2 osteoporosis-related mRNAs with ceRNA activity (COCH, RARG) as promising candidate downstream mRNAs of miR-1303." (PMID 36717952, 2023). "Surprisingly, qRT-PCR showed that the elevation of RARG in the osteoporosis subjects was not significant, while the mRNA level of COCH was increased significantly." (PMID 36717952, 2023). "However, by performing qRT-PCR, we found that COCH was increased significantly while RARG showed a mild elevation without statistic difference in the osteoporosis subjects compared to the control subjects." (PMID 36717952, 2023).